TRAV25 (T cell receptor alpha variable 25)
Description:
V region of the variable domain of T cell receptor (TR) alpha chain that participates in the antigen recognition. Alpha-beta T cell receptors are antigen specific receptors which are essential to the immune response and are present on the cell surface of T lymphocytes. Recognize peptide-major histocompatibility (MH) (pMH) complexes that are displayed by antigen presenting cells (APC), a prerequisite for efficient T cell adaptive immunity against pathogens. Binding of alpha-beta TR to pMH complex initiates TR-CD3 clustering on the cell surface and intracellular activation of LCK that phosphorylates the ITAM motifs of CD3G, CD3D, CD3E and CD247 enabling the recruitment of ZAP70. In turn ZAP70 phosphorylates LAT, which recruits numerous signaling molecules to form the LAT signalosome. The LAT signalosome propagates signal branching to three major signaling pathways, the calcium, the mitogen-activated protein kinase (MAPK) kinase and the nuclear factor NF-kappa-B (NF-kB) pathways, leading to the mobilization of transcription factors that are critical for gene expression and essential for T cell growth and differentiation. The T cell repertoire is generated in the thymus, by V-(D)-J rearrangement. This repertoire is then shaped by intrathymic selection events to generate a peripheral T cell pool of self-MH restricted, non-autoaggressive T cells. Post-thymic interaction of alpha-beta TR with the pMH complexes shapes TR structural and functional avidity.
Synonyms: TCRAV25S1; TCRAV32S1
Gene: T-cell receptor variable (V) gene on chromosome 14 (22,112,347 to 22,113,031, forward strand). Ensembl gene ENSG00000211806.
Subcellular location: Cell membrane
Gene Ontology:
Biological process: response to bacterium
Cellular component: plasma membrane
Homologues: Paralogues in human: TRAV27 (58% identical), TRAV30 (42% identical), TRAV17 (40% identical), TRAV20 (40% identical), TRAV34 (40% identical), TRAV39 (39% identical), TRAV10 (37% identical), TRAV6 (37% identical), TRAV36DV7 (35% identical), TRAV13-1 (33% identical), TRAV21 (33% identical), TRAV7 (33% identical), and 11 more.
Diseases named in the same sentence as TRAV25 in open-access papers:
TRAV25 is named in the same sentence as 1 disease in open-access papers, as found by Europe PMC text mining. Sharing a sentence is not in itself a finding about the gene and the disease.
TRAV25 shares sentences with these, for which no sentence is quoted: COVID-19 (1 paper).